ME1 (malic enzyme 1)
Diseases named in the same sentence as ME1 in open-access papers (continued):
Sharing a sentence is not in itself a finding about the gene and the disease.
tumor (40 papers, 2015 to 2026). "In our analysis of tumor stemness, we identified a significant association between the ME1 gene and tumor stemness scores across 14 tumor types." (PMID 40510340, 2025). "Functional enrichment analysis and single-cell analysis indicated that ME1 expression was associated with metabolic regulation, macrophage immune responses, antioxidant defense mechanisms, and the potential tumor microenvironment." (PMID 40510340, 2025). "Since hypoxia is strongly involved in tumor budding, we examined the energy metabolism associated with the hypoxic environment and found that ME1 expression and lactate levels were increased." (PMID 32998265, 2020). "The association between ME1 expression and tumour stage in a human CRC TMA comprising 1,260 specimens was in line with our results demonstrating the importance of glutaminolysis for CRC growth." (PMID 26948869, 2016). "We found consistently significant dependencies between the pathological tumour stage (pT stage, that is, the extent of local invasion into the bowel wall) and expression of ME1 (linear by linear association test, P<0.001)." (PMID 26948869, 2016). "The suppression of ME1 gene expression is associated with a reduction in the transformation and migration of epithelial cells, while simultaneously promoting oxidative stress and apoptosis in tumor cells." (PMID 40510340, 2025). "Furthermore, upregulation of ME1 was significantly associated with more advanced pathological stages (p < 0.001), pT stage (p < 0.001) and tumour grade (p < 0.001)." (PMID 38445776, 2024). "We characterized the male progeny of the novel intercross of heterozygous male ApcMin/+ mice with female ME1-Tg mice, namely, ApcMin/+ mice with intestine-specific augmentation of ME1 (designated ApcMin/+/ME1-Tg) for tumor parameters and for expression of candidate tumor-associated genes." (PMID 30250042, 2018). "In addition, ME1 is associated with tumor growth, lung metastasis, peritoneal dissemination, and shorter overall and disease-free survival in gastric cancer cases." (PMID 30115834, 2018). "For example, ME1 expression is known to be regulated by Nrf2, and tumours with mutated Keap1 or Nrf2 genes could be dependent on ME1 and thus be sensitive to ME1 inhibition." (PMID 28481367, 2017). "Consistently, hepatocyte-specific Me1 knockout (Me1HKO) mice treated with diethylnitrosamine (DEN) showed reduced tumor burden as compared to Me1Flox mice." (PMID 41881958, 2026). "By analyzing the relationship between ME1 expression and immune regulation genes, immune examination points, and immune infiltration, we revealed the significant role of ME1 in the tumor microenvironment." (PMID 40510340, 2025). "In this study, we identified intriguing associations between ME1 expression and TMB, MSI, and tumor stemness." (PMID 40510340, 2025). "In this study, we demonstrated the expression of ME1 in both tumor and normal tissues, including the colon, lung, liver, testis, cervix, and thyroid gland, utilizing data from the HPA database." (PMID 40510340, 2025). "In oral SCC (OSCC), ME1 is overexpressed in 48% of cases and correlates with tumor factors such as T stage, N stage, clinical stage, and histological grade." (PMID 39996805, 2025). "ME1 appears to play a crucial role in facilitating immune cell infiltration into the tumor microenvironment." (PMID 40510340, 2025). "As a master regulator of NADPH homeostasis, ME1 fuels tumor cell survival under metabolic stress by sustaining glutamine recycling, fatty acid biosynthesis, glycolytic flux, and reactive oxygen species (ROS) detoxification." (PMID 40906080, 2025). "Future research should employ conditional knockout models or single-cell metabolomics to elucidate the specific mechanisms by which ME1 contributes to tumor immune evasion." (PMID 40510340, 2025).
tumor (continued). "Initially, we utilized the SMART platform to assess the DNA methylation levels of ME1 in tumor tissues compared to their corresponding normal tissues, as sourced from the TCGA database." (PMID 40510340, 2025). "The left panel illustrates the expression of ME1 in the corresponding tumor tissues, while the right panel represents its expression in normal tissues." (PMID 40510340, 2025). "We analyzed and verified the expression of ME1 in both tumor and normal tissues at the mRNA and protein levels." (PMID 40510340, 2025). "We investigated the immune regulatory role of ME1 in tumors by analyzing its correlation with immune regulatory genes, immune checkpoints, tumor stemness scores, and immune infiltration." (PMID 40510340, 2025). "This inverse correlation suggests a potential host-driven anti-tumor mechanism involving ME1 inhibition to disrupt NADPH-dependent pro-tumorigenic pathways." (PMID 40906080, 2025). "In gastrointestinal cancer, the ME1 phenotype is characterized by important adipogenic components and paracrine communication between tumors and adjacent non-tumor tissues." (PMID 39996805, 2025). "By integrating single-cell sequencing technology, we aim to analyze the cell type-specific expression patterns of ME1 within the tumor microenvironment." (PMID 40510340, 2025). "The in vitro experiments conducted in this study primarily focus on the impact of ME1 on the functional phenotypes of tumor cells." (PMID 40510340, 2025). "The Estimate Algorithm assessed the correlation between ME1 expression and the tumor immunochemical microenvironment." (PMID 40510340, 2025). "We observed a significant correlation between the expression levels of the ME1 gene and tumor immune infiltration scores." (PMID 40510340, 2025). "Thirdly, The in vitro experiments conducted in this study focused on the impact of ME1 on the autonomous behavior of tumor cells; however, the efficacy of immunotherapy involves complex tumor-immune interactions." (PMID 40510340, 2025). "By controlling the cellular levels of NADPH, it is involved in redox homeostasis, and a role of ME1 in tumor progression through its ability to reduce intracellular ROS levels is described." (PMID 39858101, 2025). "In tumor cells, decreased ME1 gene expression or inhibition of ME1 activity results in decreased cell proliferation, epithelial–mesenchymal transition, and migration in vitro, which in turn promote oxidative stress, apoptosis, and/or cellular senescence." (PMID 36936412, 2023). "In the highly metastatic HSC3 subcutaneous tumor model, HOXA11-AS knockdown inhibited tumor growth by 25% more than lanthanide inhibition of ME1, a putative mediator of NQO1." (PMID 36142607, 2022). "Further investigation showed that circME1 interacts with U1 snRNP and promotes transcription of its parental gene ME1 in cis, thereby promoting tumor development and sunitinib resistance." (PMID 35798876, 2022). "Taken together, these results indicate that circME1 enhances ccRCC tumor growth and metastasis mainly through ME1." (PMID 35798876, 2022). "To clarify the relationship between tumor budding and ME1 in OSCC, we performed immunostaining of the epithelial marker AE1/AE3 and of ME1 in 96 specimens of OSCC." (PMID 32998265, 2020). "Our study also showed that alterations in HIF1α and ME1 expression occurred concomitantly, suggesting a relationship between tumor budding and hypoxia." (PMID 32998265, 2020). "Exploring the therapeutic potential of ME1 in cell line–based as well as patient derived xenograft models, gene silencing of ME1 significantly suppressed tumor growth increasing cell apoptosis." (PMID 31881713, 2019). "We performed tumor xenograft experiment in which the mammary fat pads of female SCID mice were injected with SUM159 cells with stable empty vector or knockdown of ME1 expression." (PMID 30425310, 2018).
tumor (continued). "SUM159 cells with stable knockdown of ME1 expression had dramatically reduced tumor growth compared with their corresponding vector cells, suggesting that ME1 is critical for tumorigenicity of BLBC cells." (PMID 30425310, 2018). "Malic enzyme’s isoforms ME2 and ME3 reside in mitochondria whereas ME1 is cytosolic, and all of them are frequently overexpressed in tumor tissues of diverse origin." (PMID 26869992, 2016). "The elevated expression of ME1 in macrophages may suggest its involvement in metabolic regulation, immune response, antioxidant defense, immune tolerance, and potentially the tumor microenvironment." (PMID 40510340, 2025). "This suggests that ME1 may play a pivotal role in tumor development by modulating the immune response and promoting tumor invasion." (PMID 40510340, 2025). "By influencing TMB, MSI, and tumor differentiation, ME1 may play a regulatory role in anti-tumor immune responses." (PMID 40510340, 2025). "Conversely, the overexpression of ME1 appeared to promote tumor cell proliferation and migration." (PMID 40510340, 2025). "In addition, to investigate the potential of ME1 as a target for tumor immunotherapy, we analyzed the overall survival rates of patients exhibiting high versus low expression of ME1 following treatment with anti-PD1, anti-PDL1, or anti-CTLA4 therapies." (PMID 40510340, 2025). "We hypothesize that ME1 may participate in the tumor immune microenvironment through metabolic-immune crosstalk and the regulation of immune checkpoints." (PMID 40510340, 2025). "ME1 primarily participates in lipid metabolism and tumor progression." (PMID 38836761, 2024). "We also found that circME1 exerted diverse oncogenic functions in ccRCC tumor progression and sunitinib resistance development, which could be dramatically repressed by ME1 inhibitor." (PMID 35798876, 2022). "A significant correlation was observed between tumor budding and ME1 expression." (PMID 32998265, 2020). "Furthermore, when the correlation between tumor budding and ME1 expression was compared with T factor, N factor, and stage, a stronger correlation was observed in cases that progressed with respect to all factors." (PMID 32998265, 2020). "In the future, the discovery of a more useful ME1 inhibitor is desired for targeting tumor budding." (PMID 32998265, 2020). "This suggests that tumor budding and ME1 are deeply involved in the progression of OSCC." (PMID 32998265, 2020). "Here, we have used this mouse model to test the hypothesis that ME1 overexpression would lead to increased tumor burden." (PMID 30250042, 2018). "Indeed, we demonstrated that ME1 expression promoted, whereas knockdown of ME1 attenuated adaptation of tumor cells to hypoxic environment." (PMID 30425310, 2018). "To examine the role of ME1 in tumor genesis of the gastrointestinal tract, we crossed mice having augmented intestinal epithelial expression of ME1 (ME1-Tg mice) with ApcMin/+ mice to obtain male ApcMin/+/ME1-Tg mice." (PMID 30250042, 2018). "Since inhibiting ME1 suppressed tumor growth and increased survival time in a mouse tumor model, ME1 could be a valid target for molecular therapy in OSCC." (PMID 30115834, 2018). "Therefore, the efficacy of ME1 inhibition on tumour growth suppression probably depends on the tumour microenvironment, and in vivo experiments are necessary to clarify the issue." (PMID 28481367, 2017). "An in vivo efficacy study is needed to verify whether ME1 inhibition is effective as a tumour growth suppressor." (PMID 28481367, 2017). "Tumours sensitive to ME1 inhibition should therefore be selected." (PMID 28481367, 2017). "We hypothesize that ME1 levels might be elevated during loco-regional spread of tumour cells when tumour cells still need a basal aerobic respiration." (PMID 26948869, 2016).
tumor (continued). "We hypothesized that mutant KRAS can regulate glutamine metabolism genes in NSCLC and maintain tumor redox balance through transamination reactions that generate cytosolic NADPH via malic enzyme 1 (ME1), which may contribute to radioresistance." (PMID 26173780, 2015). "We next assessed whether ME1 was essential for tumor and organoid growth." (PMID 32648540, 2020). "Therefore, we investigated the role of ME1 in tumor budding in OSCC." (PMID 32998265, 2020). "Alternatively a glucose-depleted microenvironment could make tumours sensitive to ME1 inhibition." (PMID 28481367, 2017). "Here, we first evaluated the clinical significance of malic enzyme 1 (ME1) in HCC patients and revealed that ME1 was significantly upregulated in tumor tissues and positively correlated with poor prognosis." (PMID 41881958, 2026). "ME1 plays a significant role in regulating the supply of NADPH, oxidative stress, lipid metabolism, and immunosuppression within the tumor microenvironment through metabolic reprogramming." (PMID 40510340, 2025). "Among the various tumors analyzed, ME1 demonstrated a significant correlation with methylation levels, TMB, MSI, immune checkpoints, immunomodulatory regulatory genes, tumor microenvironment scores, and immune infiltration." (PMID 40510340, 2025). "Therefore, tumor budding and ME1 expression may be useful markers of OSCC malignancy." (PMID 39996805, 2025). "ME1 expression is also significantly correlated with speedy/RINGO cell cycle regulator family member C (SPDYC), which influences the tumor immune microenvironment and lipid metabolism." (PMID 39996805, 2025). "SMS can influence the metabolic process and is involved in tumor growth.Overexpression of ACACA, ME1, ADSL or S100A10 promotes HCC growth, migration or invasion, and is connected with poor prognosis." (PMID 36632140, 2023). "By calculating the correlation coefficients between each module and clinical traits, we finally determined that ME1 and ME4 modules were closely related to tumours." (PMID 37775993, 2023). "An acidic tumor microenvironment, linked with a hypoxic environment, promotes the expression of malic enzyme 1 and brings EMT to tumor cells through YAP1 activation." (PMID 36982569, 2023). "We previously reported that in OSCC, enhanced glutaminolysis mediated by ME1 expression leads to budding, enhanced stemness, induction of EMT, and acquisition of metastatic potential at the leading edge of tumor invasion." (PMID 36142607, 2022). "Using bioinformatics, we screened six genes for their potential to influence tumor lipid metabolism (ADH1C, APEX1, ME1, S100A10, ACACA, and CYP2C9), and a prognosis model for HCC patients was constructed." (PMID 36456877, 2022). "Malic enzyme 1 contributes to pyruvate carboxylation activity in PDAC cells and is important for tumor growth." (PMID 32648540, 2020). "Tumor budding was measured in 96 human OSCCs by immunostaining for an epithelial marker (AE1/AE3), and its expression was compared with that of ME1." (PMID 32998265, 2020). "Tumor budding and ME1 expression are thus considered useful markers of OSCC malignancy, and ME1 is expected to be a relevant target for molecular therapy." (PMID 32998265, 2020). "For 7 SCC-distinguishing enzymes (ASNS, GAPDH, GOT2, IDH2, ME1, PSAT, and TPI) protein levels were increased in MYC+N1ICD tumours compared with the normal lungs." (PMID 31114017, 2019). "We then analyzed the relationship between ME1 expression and histological grades of the tumors in GSE25066, NKI295, and GSE1456 datasets in which tumors had been scored for tumor grade." (PMID 30425310, 2018). "Our experimental data suggested that ME1 promotes cancer progression by increasing lactate fermentation, maintaining redox status, acquiring stemness and EMT phenotype, and promoting tumor growth and invasion in OSCC cells." (PMID 30115834, 2018).
tumor (continued). "In OSCC, ME1 expression leads to a shift in energy metabolism from OXPHOS to glycolysis, resulting in decreased oxygen consumption and increased lactate production, which in turn promote tumor formation and growth." (PMID 39996805, 2025). "Mechanistically, ME1 links glycolysis, the TCA cycle, and the generation of NADPH, which are crucial for maintaining redox balance, lipid synthesis, and immune cell function within the tumor microenvironment." (PMID 40510340, 2025). "We infer that ME1 may regulate the metabolic state of T cells through NADPH-dependent redox homeostasis, thereby affecting their activation and anti-tumor functions." (PMID 40510340, 2025). "ME1 expression was low in cases where budding was not seen at the tumor front, whereas it was higher in cases where budding was observed at the tumor front." (PMID 32998265, 2020). "In addition, we demonstrated that ME1 potentially refines the ELN risk categorization for HSCT-treated patients, while also being correlated with a tumor-supportive microenvironment, non-GMP-like AML blasts subtype, and specific AML drug sensitivity." (PMID 36612292, 2022). "Moreover, lactate and glutamine support NADPH production via isocitrate dehydrogenase 1 (IDH1) and malic enzyme 1 (ME1), respectively, under glucose-deprived conditions, and ME1 can synergize with mitochondrial IDH2 to maintain antioxidant systems to support tumor growth and metastasis." (PMID 35873566, 2022). "What is more, in tumor cells glutamine entry to TCA cycle improves not only carbon supply for macromolecules build-up, it also may replenish pool of cellular NADPH, since the conversion of malate to pyruvate catalyzed by ME1 is accompanied by a reduction of NADP+ molecule." (PMID 29958416, 2018). "qRT-PCR revealed significant upregulation of CXCL10, CXCL11, ME1, MT1X, FAT1, OAS2, and MT2A in tumor tissues compared to normal tissues." (PMID 40574841, 2025). "We hypothesise that a treatment strategy combining an ME1 inhibitor with an inhibitor of glycolysis, such as 2-DG, or with an inhibitor of glucose transporter, such as GLUT-4 inhibitor, could result in a synergic action against the tumour regardless of tumour microenvironment." (PMID 28481367, 2017).
infection (5 papers, 2019 to 2025). The state of being infected such as from the introduction of a foreign agent such as serum, vaccine, antigenic substance or organism. "Our results establish H3K4me2 as a unique modification induced by infection, distinct from H3K4me3 or me1, which localizes to enhancer regions genome-wide." (PMID 38956024, 2024).
adenocarcinoma (1 paper, 2025). A common cancer characterized by the presence of malignant glandular cells. "In NSCLC, ME1 is more strongly expressed in squamous cell carcinoma (SCC) than in adenocarcinoma and is correlated with smoking and poor prognosis." (PMID 39996805, 2025).
ME1 also shares sentences with these, for which no sentence is quoted: asthma (2 papers); glioblastoma (2); hearing loss (2); adrenocortical carcinoma (1); Alzheimer disease (1); bladder cancer (1); breast tumors (1); cervical carcinoma (1); cervical squamous cell carcinoma (1); cholangiocarcinoma (1); colon adenocarcinoma (1); colon adenoma (1); colorectal (1); endometrial cancer (1); endometriosis (1); esophageal carcinoma (1); head and neck squamous cell carcinoma (1); Hyperglycemia (1); Hyperinsulinemia (1); Hypertension (1); hypertriglyceridemia (1); Hypoglycemia (1); lung adenocarcinoma (1); lung squamous cell carcinoma (1); meningioma (1); nasopharyngeal carcinoma (1); oral cancer (1); pancreatic ductal adenocarcinoma (1); pheochromocytoma and paraganglioma (1); prostate carcinoma (1).
A further 12 diseases each share a sentence with ME1 in 1 paper.